RSPO3 (R-spondin 3)
Diseases named in the same sentence as RSPO3 in open-access papers (continued):
Sharing a sentence is not in itself a finding about the gene and the disease.
mammary tumors (8 papers, 2012 to 2023). "We demonstrate that a gain in RSPO3 causes the development of poorly differentiated invasive mammary tumors in mice, providing functional evidence for the causal oncogenic capacity of RSPO3 in driving breast cancer." (PMID 36106661, 2022). "We also provide direct in vivo evidence that Rspo3 acts as an oncogenic driver in the mammary gland, as Rspo3 overexpression consistently caused the development of mammary tumors in mice." (PMID 36106661, 2022). "Adding to this, we found that a quarter of breast cancer patients harbor RSPO2 or RSPO3 copy number amplification, which is associated with high tumor grade, ER and PR negative status, and reduced survival, indicating the clinical relevance of RSPO." (PMID 36106661, 2022). "MMTV‐Cre;Rspo3inv female mice developed mammary tumors consistently, providing in vivo evidence for the causal oncogenic capacity of RSPO3 in the mammary gland." (PMID 36106661, 2022). "We found that a quarter of breast cancer patients harbor RSPO2/RSPO3 copy number amplifications, which are associated with lack of steroid hormone receptor expression and reduced patient survival." (PMID 36106661, 2022). "Moreover, we found that a quarter of breast cancer patients harbor RSPO2/RSPO3 copy number amplification, which is associated with worse prognosis and lack of steroid hormone receptor expression, restricting therapeutic options." (PMID 36106661, 2022). "In conclusion, our study identified nine key regulators, of which COL11A1, MMP11 and COL10A1 were up regulated and PCOLCE2, LAMA2, TMTC1, ADAMTS5, TIMP4 and RSPO3 were down regulated in breast cancer samples as compared to control samples." (PMID 37238942, 2023). "Among these key genes COL11A1, MMP11 and COL10A1 were highly expressed and PCOLCE2, LAMA2, TMTC1, ADAMTS5, TIMP4, and RSPO3 were having lower expression levels in breast cancer samples." (PMID 37238942, 2023). "The genes namely COL11A1, MMP11 and COL10A1 were found up regulated and PCOLCE2, LAMA2, TMTC1, ADAMTS5, TIMP4 and RSPO3 were found down regulated in breast cancer." (PMID 37238942, 2023). "Since RSPOs are most often envisioned as agonists of the canonical Wnt pathway, we studied our RSPO3 breast cancer mouse model in parallel to the WNT1‐driven counterpart." (PMID 36106661, 2022). "RSPO3‐driven mammary tumors typically show poor differentiation, areas of epithelial‐to‐mesenchymal transition, and metastatic potential." (PMID 36106661, 2022). "In RSPO3‐driven mammary tumors, K8 expression was observed throughout solid epithelial tumor structures but in a weak and patchy staining pattern." (PMID 36106661, 2022). "RSPO3‐driven mouse mammary tumors are distinct from WNT1‐driven counterparts and uniquely present with poor differentiation, malignant transformation, and metastatic potential." (PMID 36106661, 2022). "Foremost, we demonstrate the causal oncogenic capacity of RSPO3 in the breast, as conditional Rspo3 overexpression consistently drives the development of mammary adenocarcinomas in our novel Rspo3 breast cancer model." (PMID 36106661, 2022). "We also show that mammary tumors driven by RSPO3 are morphologically and molecularly distinct from WNT1‐driven tumors, with higher metastatic potential." (PMID 36106661, 2022). "Here, we assess the oncogenic capacity of RSPO in breast cancer in a direct fashion by generating and characterizing a novel mouse model with conditional Rspo3 expression in the mammary gland." (PMID 36106661, 2022). "RSPO3‐driven mammary tumors typically presented as adenocarcinomas with mixed solid acinar and ductal arrangements, focal regions of squamous metaplasia, and areas with epithelial‐to‐mesenchymal transition (EMT)." (PMID 36106661, 2022). "To look into this further, we assessed the gene expression profiles of RSPO3‐ versus WNT1‐driven mouse mammary tumors by RNA sequencing analysis of the respective mammary tumor tissues." (PMID 36106661, 2022).
mammary tumors (continued). "Given the reported interplay in the Wnt/β‐catenin pathway, we comparatively analyzed RSPO3‐driven mouse mammary tumors versus classical WNT1‐driven analogues." (PMID 36106661, 2022). "To further reveal the features of RSPO3‐driven mammary tumors, we performed immunohistochemical analyses." (PMID 36106661, 2022). "Although RSPO3‐driven mammary tumors contain both basal and luminal keratins, the relatively weak and disorganized expression patterns indicated poor differentiation." (PMID 36106661, 2022). "Histological analysis revealed that mammary tumors developing in mice with RSPO3/WNT1 co‐expression showed a mixed phenotype, typically exhibiting characteristics of both RSPO3‐ and WNT1‐driven tumors." (PMID 36106661, 2022). "Strikingly, we found that RSPO3‐driven mammary tumors appeared as completely different entities from those driven by WNT1." (PMID 36106661, 2022). "In line with histological features, lung metastases were found in 6 of 21 (29%) mice bearing RSPO3‐driven mammary tumors, mostly presenting in multitude, with up to 25 metastatic lesions per mouse." (PMID 36106661, 2022). "Co‐expression of Rspo3 and Wnt1 transduced mammary tumors with a mixed phenotype harboring morphological features characteristic of both transgenes." (PMID 36106661, 2022). "Taken together, these data indicate that over a quarter of breast cancer patients harbor RSPO2 or RSPO3 amplification, leading to a reduced clinical outcome." (PMID 36106661, 2022). "Herewith, we establish RSPO3 as a driver of breast cancer with clinical relevance, proposing RSPO3 as a novel candidate target for therapy in breast cancer." (PMID 36106661, 2022). "As patient data suggested a pro‐tumorigenic role for RSPO2 and RSPO3 in breast cancer, we aimed to determine the oncogenic potential of RSPO in breast cancer." (PMID 36106661, 2022). "Grossly, the RSPO3/WNT1 mammary tumors showed a combination of compact solid areas as well as more dilated cystic areas typically seen in RSPO3‐ or WNT1‐driven mammary tumors, respectively." (PMID 36106661, 2022). "To obtain a comprehensive insight into the molecular routes that are differentially activated in RSPO3‐driven compared with WNT1‐driven mammary tumors, we performed gene ontology analysis." (PMID 36106661, 2022). "The RSPO3‐driven mammary tumors typically appear as poorly differentiated adenocarcinomas with metastatic potential." (PMID 36106661, 2022). "This further emphasized the relatively poor differentiation of mammary tumors driven by RSPO3, together with the typical presence of EMT areas suggesting increased dissemination potential." (PMID 36106661, 2022). "In a subsequent study, Runx1 was shown to bind to the RSPO3 promoter region and upregulate its expression in mouse mammary tumours." (PMID 30987640, 2019). "In particular, RSPO3 has been described as a potent oncogene due to its ability to transform and generate mammary tumors in vivo after inoculation of RSPO3-transduced epithelial mammary cells." (PMID 26735887, 2016). "Despite this, the relatively low expression of Wnt/β‐catenin target genes in RSPO3‐driven mammary tumors suggests that tumorigenesis driven by RSPO3 might be less reliant on Wnt/β‐catenin pathway activation." (PMID 36106661, 2022). "Instead, or in parallel, RSPO3 might rely on alternative molecular routes and, supportively, 198 genes were upregulated in RSPO3‐driven mammary tumors." (PMID 36106661, 2022). "Importantly, breast cancer patients harboring RSPO2 or RSPO3 copy number amplification showed a significantly reduced overall survival." (PMID 36106661, 2022). "Therefore, we examined the lungs of mice bearing WNT1‐ or RSPO3‐driven mammary tumors to determine distant metastasis potential." (PMID 36106661, 2022). "Likewise, we demonstrate that upregulation of Foxp3 expression in mammary tumor cells reduces Rspo3 gene expression." (PMID 26735887, 2016).
mammary tumors (continued). "Similar expression profile of seven among nine genes (except ADAMTS5 and RSPO3) was validated in MCF-7 and MDA-MB-231 human breast cancer cell lines." (PMID 37238942, 2023). "These morphological differences were further substantiated upon RNA sequencing analysis, which revealed that RSPO3‐ and WNT1‐driven mammary tumors have distinctive molecular profiles." (PMID 36106661, 2022). "The mammary tumors that developed in MMTV‐Cre;Rspo3inv mice (i.e. RSPO3‐driven tumors) macroscopically appeared as solid, compact structures, confirmed microscopically by H&E staining." (PMID 36106661, 2022). "In breast cancer patients, RSPO2, RSPO3, and RSPO4 overexpression has been reported, which is associated with hormone receptor‐negative tumor status and for RSPO2 also with reduced patient survival." (PMID 36106661, 2022). "Altogether, in line with the different tumor morphologies of RSPO3‐ and WNT1‐driven mammary tumors, gene expression analysis revealed that their molecular profiles are also distinct." (PMID 36106661, 2022). "To put this poorly differentiated RSPO3 tumor phenotype into further perspective, we comparatively analyzed WNT1‐driven mammary tumors that developed in the co‐bred MMTV‐Wnt1;Rspo3inv cohort (only Wnt1 transgene expression, given the lack of Cre)." (PMID 36106661, 2022). "In summary, we report that a quarter of breast cancer patients harbor RSPO2/RSPO3 copy number gains, and these patients have a worse prognosis, whilst providing in vivo evidence that RSPO3 drives poorly differentiated invasive breast cancer in mice." (PMID 36106661, 2022). "Rspo2 and Rspo3 were firstly identified as sites of integration for MMTV-induced mammary tumors in mice, which suggest a role of Rspos as breast cancer oncogenes." (PMID 30337838, 2018). "We then investigated the potential role of Runx1 in the regulation of Rspo3 gene expression, in the LM3 cell line, which was derived from a spontaneous BALB/c mouse mammary tumor." (PMID 26735887, 2016). "First, RSPO3‐driven mammary tumors were largely negative for the steroid hormone receptors ERα and PR." (PMID 36106661, 2022). "In the same report, normal mouse mammary tumours transduced to express RSPO3, but not the empty vector controls, produced tumours." (PMID 30987640, 2019). "Furthermore, we demonstrate that Runx1 is able to actively promote oncogene Rspo3 and prevent GJA1 gene expression in mammary tumor cell lines." (PMID 26735887, 2016). "Overexpression of RSPO2, RSPO3, and RSPO4 has been reported in breast cancer patients, in particular in triple‐negative tumors, where enhanced RSPO2 expression was associated with reduced metastasis‐free survival." (PMID 36106661, 2022).
colorectal tumors (7 papers, 2016 to 2025). "Studies have found that targeting RSPO3 in PTPRK-RSPO3-fusion-positive human tumor xenografts promotes cell differentiation and inhibits tumor growth, in part suggesting differentiation therapy as a new clinical approach for the treatment of colorectal tumors." (PMID 37569705, 2023). "Tumours harbouring gene fusions involving RSPO2 and RSPO3 were found to occur in around 10% of colorectal tumours and result in upregulation of RSPO2 or RSPO3 expression." (PMID 30792270, 2019).
lung carcinoma (7 papers, 2019 to 2025). "R-Spondin 3 (RSPO3) is a protein previously implicated in the progression of colorectal and lung cancers." (PMID 30987640, 2019). "In lung cancer, a protumorigenic role for RSPOs has been proposed as enhanced expression of RSPO ligands was observed in a subset of lung cancer cases, and enhanced RSPO3 expression was associated with reduced patient survival." (PMID 34663878, 2021). "RSPO3 overexpression in the absence of gene fusions has been previously detected in lung cancer, where it was associated with RSPO3 hypomethylation." (PMID 33202731, 2020). "Among these, RSPO3 and miR-22 interaction have been selected in LAML (leukemia) and LUAD (lung cancer)." (PMID 35260634, 2022).
colitis (6 papers, 2016 to 2024). Inflammation of the colon. "R-spondins were found to be highly modulated during inflammation, with notably robust upregulation of Rspo2 expression during C. rodentium infection in susceptible mice and upregulation of Rspo3 expression during DSS colitis." (PMID 27046199, 2016). "Together, these results highlight Rspo3 as the dominant R-spondin in DSS colitis and provide evidence that Rspo2 and Rspo3 may respond to specific pathogenic and inflammatory signals that differ between the two colonic inflammation models." (PMID 27046199, 2016). "We previously reported that Rspo2 is a major determinant of susceptibility to Citrobacter rodentium-mediated colitis in mice and recent genome-wide association studies have revealed RSPO3 as a candidate Crohn’s disease-specific inflammatory bowel disease susceptibility gene in humans." (PMID 27046199, 2016). "For example, RBP1+ cells, confirmed to be a subset of GLI1+ cells, are suggested to sense DSS-induced colitis injury, thereby stimulating Rspo3 production to promote the injury recovery process." (PMID 38540281, 2024). "For instance, Grem1 and Rspo3 reportedly increased PDGFRαlo cells during colitis-induced conditions." (PMID 38540281, 2024). "To address the role of Rspo3 during the regenerative state, we induced mild colitis by using 1.5% of DSS." (PMID 31554819, 2019). "As in our model, KO mice of RSPO3 in PdgfRα+ stromal cells showed a decreased number of PCs during homeostasis, while being hypersensitive to DSS-induced colitis." (PMID 35190527, 2022). "Since Rspo3 is a major determinant of Lgr5+ stem cell identity and essential for maintaining the proliferative compartment upon DSS colitis, we asked how DSS affects the stem cell pool." (PMID 31554819, 2019). "Both RSPO3 and yes-associated protein (YAP) signaling were recently shown to be important for colonic injury repair upon dextran sulfate sodium–induced (DSS-induced) colitis, but their relationship has not been investigated." (PMID 36099044, 2022).
lung adenocarcinoma (6 papers, 2016 to 2022). A carcinoma that arises from the lung and is characterized by the presence of malignant glandular epithelial cells. "RSPO3 was reported to promote tumor aggressiveness in Keap1-deficient lung adenocarcinomas." (PMID 27980454, 2016). "The findings of these authors suggest that RSPO3 overexpression may potentially act as a driving mechanism behind the aggressiveness of Keap1-deficient lung adenocarcinomas." (PMID 27980454, 2016). "There are several oncogenic proteins such as EPHA3 and RSPO1, RSPO2, and RSPO3, which are overexpressed in lung adenocarcinomas and lymphoblastic leukemia and define the patient’s survival rates." (PMID 36139498, 2022). "Little has been reported regarding patient outcomes according to RSPO3 expression status; however, one report described RSPO3 overexpression in a subset of primary lung adenocarcinoma samples, with poorer overall survival in patients with higher expression." (PMID 30987640, 2019). "With respect to other cancers, contribution of RSPO3 expression to patient survival has been addressed in one study, which reported a survival detriment in lung adenocarcinoma." (PMID 30987640, 2019). "We found that RSPO3, ADAMTS8, DMBT1, DOCK8, STMN2, SPINK6 and TUSC3 were the co-genes of HOXA11-AS in lung adenocarcinoma whereas RSPO3, ADAMTS8, DMBT1, DOCK8, STMN2, SPINK6, TUSC3 and C8orf22 were the co-genes of HOXA11-AS in squamous cell carcinoma." (PMID 27980454, 2016). "In lung adenocarcinoma tissues, RSPO3 was obviously more highly expressed in the advanced stages (III and IV) than the early stages (I–II, t = −2.462, P = 0.015)." (PMID 27980454, 2016). "Interestingly, this association may be histopathology-specific, as a separate study showed RSPO3 downregulation in squamous cell lung cancer, but upregulation in lung adenocarcinoma, compared to normal lung tissue." (PMID 30987640, 2019). "Additionally, the original data from TCGA verified that ADAMTS8, DMBT1 and DOCK8 were downregulated in both lung adenocarcinoma and squamous cell carcinoma, whereas RSPO3 expression was upregulated in lung adenocarcinoma and downregulated in lung squamous cell carcinoma." (PMID 27980454, 2016). "In addition, RSPO3, ADAMTS8 and DOCK8 were related to overall survival and disease-free survival (all P < 0.05) of lung adenocarcinoma patients in TCGA." (PMID 27980454, 2016). "Furthermore, RSPO3, ADAMTS8 and DOCK8 were also related to the overall survival and disease-free survival of lung adenocarcinoma patients in the TCGA data." (PMID 27980454, 2016).
gastric cancer (5 papers, 2022 to 2024). A primary or metastatic malignant neoplasm involving the stomach. "For instance, in line with our results, a recently published atlas of gastric cancer TME also found RSPO3 signaling in fibroblasts and Notch signaling in endothelial cells." (PMID 36550535, 2022). "While we find that high expression of RSPO3 in the stroma can result from injury and infection, elevated R-spondin signaling can also occur as a result of a mutational event in genes such as RNF43, which is observed in a subset of patients with gastric cancer." (PMID 36099044, 2022). "Researchers discovered communications between CAFs and gastric cancer cells via integrin receptor interactions with collagen, fibronectin, thrombospondin 1 (THBS1) ligands, and leucine rich repeat containing G protein-coupled receptor 4 (LGR4)- R-spondin 3 (RSPO3), which regulate stemness." (PMID 36154923, 2022). "Furthermore, the “SPEM” gene set as well as the “gastric cancer” gene set showed significant negative enrichment in infected Rspo3-KO mice compared with WT and positive enrichment in infected Rspo3-KI mice compared with WT littermates." (PMID 36099044, 2022).